GJA1 (gap junction protein alpha 1)
Description:
Structural component of the gap junction, a specialized intercellular structure consisting of a cluster of closely packed pairs of transmembrane channels, the connexons, that allow passage of small molecules and electrical signals between neighboring cells (By similarity). Forms homotypic and heterotypic channels gated by transjunctional voltage (By similarity). May play a critical role in the physiology of hearing by participating in the recycling of potassium to the cochlear endolymph (Probable). Negative regulator of bladder functional capacity: acts by enhancing intercellular electrical and chemical transmission, thus sensitizing bladder muscles to cholinergic neural stimuli and causing them to contract (By similarity). May play a role in the conductive system of ventricular myocardium and heart morphogenesis (By similarity). May play a role in cell growth inhibition through the regulation of NOV expression and localization (By similarity). Involved in intercellular innate immune signaling. Mediates translocation of 2',3'-cGAMP and 2',5'-oligoadenylates (2-5A) second messengers from virus-infected cells to macrophages and uninfected neighboring cells to propagate and amplify the antiviral immune response.
Synonyms: Cx43; GJAL; ODD; ODOD; SDTY3; AVSD3; CMDR; EKVP; EKVP3; HLHS1; HSS; ODDD; PPKCA
Tractability: Small molecule: a structure with a bound ligand is known; a high-quality ligand is known. Antibody: UniProt places it where antibodies can reach, with high confidence; its Gene Ontology location is reachable by antibodies, with high confidence; UniProt predicts a signal peptide or a membrane-spanning region. PROTAC: UniProt records ubiquitination sites on it; ubiquitination databases record sites on it; its protein half-life has been measured; a small molecule that binds it is known.
Gene: Protein-coding gene on chromosome 6 (121,435,577 to 121,449,727, forward strand). Ensembl gene ENSG00000152661.
Subcellular location: Cell membrane; Cell junction, gap junction; Endoplasmic reticulum; Cell junction
Subcellular location (Human Protein Atlas): Cell Junctions; Vesicles; Nucleoplasm
Pathways (Reactome):
Vesicle-mediated transport: Formation of annular gap junctions; Gap junction assembly; Gap junction degradation; Microtubule-dependent trafficking of connexons from Golgi to the plasma membrane; Oligomerization of connexins into connexons; Regulation of gap junction activity; Transport of connexins along the secretory pathway
Signal Transduction: RHOJ GTPase cycle; RHOQ GTPase cycle
Cellular responses to stimuli: Mechanical load activates signaling by PIEZO1 and integrins in osteocytes
Disease: SARS-CoV-2 targets PDZ proteins in cell-cell junction
Gene Ontology:
Molecular function: beta-catenin binding; gap junction channel activity; gap junction channel activity involved in cell communication by electrical coupling; gap junction hemi-channel activity; monoatomic ion transmembrane transporter activity; protein binding; tubulin binding; efflux transmembrane transporter activity; gap junction channel activity involved in cardiac conduction electrical coupling; glutathione transmembrane transporter activity; beta-tubulin binding; protein tyrosine kinase binding; scaffold protein binding; signaling receptor binding; transmembrane transporter activity
Biological process: cell communication by electrical coupling; cell-cell signaling; establishment of mitotic spindle orientation; intracellular protein localization; monoatomic ion transmembrane transport; negative regulation of gonadotropin secretion; negative regulation of trophoblast cell migration; positive regulation of canonical NF-kappaB signal transduction; positive regulation of gene expression; positive regulation of mesodermal cell differentiation; positive regulation of morphogenesis of an epithelium; positive regulation of stem cell proliferation; positive regulation of vascular associated smooth muscle cell proliferation; signal transduction; atrial cardiac muscle cell action potential; bone development; bone remodeling; cardiac conduction system development; cell communication by electrical coupling involved in cardiac conduction; cellular response to amyloid-beta; export across plasma membrane; gap junction assembly; glutamate secretion; heart development; maintenance of blood-brain barrier; and 12 more
Cellular component: cell junction; cell-cell contact zone; cell-cell junction; cytoplasm; focal adhesion; gap junction; intercalated disc; mitochondrion; plasma membrane; tight junction; anchoring junction; apical plasma membrane; connexin complex; endoplasmic reticulum; endoplasmic reticulum membrane; Golgi apparatus; Golgi membrane; Golgi-associated vesicle membrane; membrane raft; contractile muscle fiber; cytosol; fascia adherens; intermediate filament; lateral plasma membrane; membrane
Genetic constraint (gnomAD): Loss-of-function variants: 9 observed, 30.09 expected, observed/expected ratio (o/e) 0.3, 90% interval 0.18 to 0.52. The upper end of that interval is the gene's LOEUF score, 0.52, which puts it in group 2 of 6, group 1 being the genes least tolerant of losing a copy. Missense variants: 278 observed, 481.34 expected, observed/expected ratio (o/e) 0.58, 90% interval 0.52 to 0.64. Synonymous variants: 186 observed, 184.12 expected, observed/expected ratio (o/e) 1.01, 90% interval 0.9 to 1.14.
Gene-disease validity (ClinGen):
ClinGen rates the evidence that GJA1 causes each of these diseases.
congenital heart disease (inheritance undetermined): Limited. A heart disease that is present at birth.
nonsyndromic genetic hearing loss (autosomal dominant): Disputed. A disease characterized by hearing loss that is not part of a larger syndrome.
Homologues: Orthologues: macaque GJA1 (99% identical), dog GJA1 (98% identical), pig GJA1 (98% identical), rat Gja1 (98% identical), mouse Gja1 (97% identical), guinea pig GJA1 (97% identical), rabbit GJA1 (92% identical), tropical clawed frog gja1 (86% identical), zebrafish gja1b (80% identical), zebrafish gja1a (63% identical). Paralogues in human: GJA3 (44% identical), GJA4 (42% identical), GJA8 (41% identical), GJA5 (36% identical), GJA9 (35% identical), GJA10 (35% identical), GJC1 (29% identical), GJB1 (29% identical), GJB6 (29% identical), GJB2 (28% identical), GJC2 (28% identical), GJB3 (27% identical), and 8 more.
Diseases named in the same sentence as GJA1 in open-access papers:
GJA1 is named in the same sentence as 574 diseases in open-access papers, as found by Europe PMC text mining. Sharing a sentence is not in itself a finding about the gene and the disease. The quoted sentences say what the papers report.
Arrhythmia (186 papers, 2008 to 2026). Any cardiac rhythm other than the normal sinus rhythm. "Cardiac gap junction connexins Cx40 (GJA5) and Cx43 (GJA1) have been implicated to have a role in developing arrhythmia and cardiac anomalies, including ToF." (PMID 41472692, 2025). "Reduced GJA1-20k levels are associated with disrupted Cx43 trafficking and mitochondrial dysfunction, contributing to cardiovascular diseases such as arrhythmias and heart failure." (PMID 39765713, 2024). "Overexpression of MiR-19a is potentially associated with an increased risk of cardiac arrhythmias, as it targets GJA1." (PMID 39456716, 2024). "Alterations of Gja1 have been associated with abnormal impulse propagation and a steep increase in arrhythmia susceptibility." (PMID 36695670, 2023). "Further, single-nucleotide polymorphisms (SNPs) of the GJA1 gene (Cx43 coding gene) correlate with primary hypertension (locus rs1925223), congenital heart disease (locus rs2071166), and arrhythmia (locus rs1925223)." (PMID 33324328, 2020). "Strategies that aim to enhance GJA1-20k expression or mimic its activity could potentially improve cardiac function, reduce the risk of arrhythmias, and protect the heart from ischemia/reperfusion injury." (PMID 39765713, 2024). "miR-19b contributed to cardiac arrhythmia through repression of gap junction protein α1 (GJA1) in a mouse model of VMC." (PMID 32269577, 2020). "Reduction of GJA1, particularly in VMC, has been implicated to decrease the conduction velocity and increase the arrhythmia susceptibility." (PMID 27213338, 2016). "For instance, miR-23a participates in estrogen deficiency-induced gap junction remodeling of rats by targeting GJA1, while miR-130a was found to downregulate GJA1, resulting in cardiac arrhythmias." (PMID 27213338, 2016). "It is well-known that changes in cardiac GJA1 expression induce arrhythmia, which is evidence of major functional changes in the heart." (PMID 25099633, 2014). "Numerous investigations have utilized in vivo models involving mice or rats to examine the regulatory effects of miRNAs such as miR-1, miR-130a, miR-206, miR-27b, and novel-miR-17 on arrhythmia through the downregulation of critical proteins including Cx43, Kir2.1, Gja1, and CACNA2D2." (PMID 41226851, 2025). "The involvement of GJA1-20k in these processes confers it great therapeutic potential, especially in treating cardiovascular diseases such as myocardial infarction, ischemia/reperfusion injuries, and arrhythmias." (PMID 39765713, 2024). "GJA1 decrease may constitute a substrate for arrhythmia, as it facilitates ventricular rendering, leading to re-entry formation." (PMID 39456716, 2024). "For example, the terms cardiac muscle contraction or regulation of ventricular cardiac muscle cell depolarization were enriched for Cardiac Arrhythmia, including genes such as Gap Junction Protein Alpha 1 (GJA) and T-Box Transcription Factor 5 (TBX5) with known roles in the disease." (PMID 37491351, 2023). "Similarly, GJA1 gene SNPs correlate with primary hypertension, congenital heart disease, and arrhythmia." (PMID 33324328, 2020). "Our findings were in consistent with a previous study which showed overexpression of miR-19b could induce arrhythmias by targeting the GJA1 in transgenic mice." (PMID 27213338, 2016). "In all, our data suggest that miR-19b may contribute to cardiac arrhythmia through repression of GJA1 in VMC." (PMID 27213338, 2016). "Based on previous studies and the present observation, it is conclusive that miR-19b may contribute to cardiac arrhythmia by repression of GJA1 in VMC." (PMID 27213338, 2016). "Four proteins (GJA1, TPM2, GJA5 and C1QBP) were related with cardiac arrhythmias, cardiac dysfunction and cardiac cell damage, and might also be responsible for DCM." (PMID 23940716, 2013).
Arrhythmia (continued). "Up-regulation of miR-1 in MI mice might be involved in the development of life-threatening arrhythmias such as ventricular tachycardia (VT), ventricular fibrillation, and atrioventricular block (AVB) by targeting the mRNAs of ion channel genes, i.e., KCNJ2 and GJA1, respectively." (PMID 29212255, 2017).
breast cancer (174 papers, 2005 to 2025). A primary or metastatic malignant neoplasm involving the breast. "For instance, higher GJB2 or GJA1 protein amounts are associated with a less favorable outcome in breast cancer." (PMID 38956497, 2024). "Prior evidence indicates that elevated GJA1 expression in the HER2-positive (HER2+) subtype of breast cancer is associated with poor prognosis." (PMID 38275864, 2024). "Recently researcher found that GJA1 was associated in glioblastoma cancer cells apoptosis and promote the progression and invasion in breast cancer cells." (PMID 32888389, 2020). "To gain further insight into the role of Cx43 in breast cancer, we analyzed how the level of GJA1 mRNA expression in each subtype was associated with outcome." (PMID 29495625, 2018). "Moreover, somatic point mutation data showed that, in the TCGA cohort, only three breast cancer patients out of 977 harbored at least one GJA1 mutation, accounting for 0.31% of the tumors." (PMID 29495625, 2018). "We then speculated that GJA1 variability could be linked to the molecular heterogeneity of breast cancer." (PMID 29495625, 2018). "GJA1 encodes for connexin-43, a gap junction protein whose expression in breast cancer cells has been implicated in pulmonary metastasis, consistent with observed lung metastasis in both patients from which the ESR1-e6>YAP1 and ESR1-e6>PCDH11X fusions were identified." (PMID 30089255, 2018). "Furthermore, reactivation of the potential tumor suppressor connexin GJA1 (Cx43) leads to reduced cell migration and regulated various angiogenesis linked proteins in breast cancer cell lines." (PMID 20042109, 2009). "However, similar to our results, more recent studies using expression array-based survival curves found that a high GJA1 expression was associated with a better prognosis in ERα-positive breast cancer tumors, while an opposite trend was observed in ERα-negative tumors and Her2e tumors." (PMID 29495625, 2018). "For instance, GJIC, which are formed by GJA1 improve the adhesion of breast cancer cells to endothelial cells, paving the way for extravasation and metastasis." (PMID 38956497, 2024). "As one of the major proteins of connexin family, GJA1 played an important role in cardiovascular disease, and which was also reported to promote the metastasis of prostate cancer cells and breast cancer cells." (PMID 35279164, 2022). "Our results confirm that, in breast cancer, GJA1 is concurrently dysregulated at both the protein and the mRNA level." (PMID 29495625, 2018). "Our study has clarified the expression pattern of GJA1 mRNA in breast cancer and showed that GJA1 expression, as well as its prognostic significance, is dependent on breast cancer subtype." (PMID 29495625, 2018). "To validate our procedure, we used the HSF2 gene, a close neighbor of GJA1 on chr6q22 which shares similar copy number in 99% of TCGA’s breast cancer cases." (PMID 29495625, 2018). "Early studies first showed a dramatic downregulation of GJA1 at the mRNA and the protein level in breast cancer cell lines as well as in rat and human breast tumors." (PMID 29495625, 2018). "For the TCGA dataset, a few tumors had amplification or deletion of GJA1, compared to genes known to be amplified in breast cancer." (PMID 29495625, 2018). "GJA1, also known as connexin 43 (Cx43), has been shown to suppress mammary tumor metastasis to the lung in a mouse model." (PMID 25572662, 2015). "We also observed a strong induction of endogenous GJA1-20k in some cell lines, such as the breast cancer cell line MDA-MB-231, after Mnk1/2 inhibition by CGP 57380." (PMID 24884945, 2014). "The expression of GJA1 is often down regulated in mammary carcinoma cell lines indicating that in these cases the role of GJA1 in carcinogenesis in maintaining cell differentiation and preventing transformation into cancer cells can not be fulfilled." (PMID 23675859, 2013). "For example, defects in GJA1 function mediate the resistance of breast cancer to tamoxifen." (PMID 38454924, 2024).
breast cancer (continued). "Through its mechanism, YTHDF3 increases the translation of m6A-enriched transcripts associated with cerebral metastasis of breast cancer, such as ST6 N-Acetylgalactosaminide Alpha-2,6-Sialyltransferase 5 (ST6GALNAC5), Gap Junction Protein Alpha 1 (GJA1), and EGFR." (PMID 39342406, 2024). "YTHDF3 promotes the translation of m6A-modified mRNAs of breast cancer brain metastasis-associated genes (e.g., ST6GALNAC5, GJA1, and EGFR) by recruiting eIF3a and increasing the expression of the corresponding proteins, which ultimately affects the brain metastasis of breast cancer." (PMID 39440064, 2024). "In breast cancer, the expression of GJA1 is related to tumor subtype." (PMID 39132501, 2024). "Missense mutations in Cx43 (GJA1) and Cx47 (GJC2) are each linked to the development of lymphedema in humans, and women with mutations in GJC2 have an increased likelihood of developing lymphedema after breast cancer surgery." (PMID 39074069, 2024). "For example, users may be curious not only how metformin is related to breast cancer, but also how the GJA1 gene might be involved in insomnia." (PMID 36711546, 2023). "However, as with grade, pooling breast cancer subtypes to analyze the effect of GJA1 on the outcome introduces biases." (PMID 29495625, 2018). "Together, these results argue that loss or amplification of the GJA1 gene likely does not dictate mRNA and protein dysregulation in breast cancer." (PMID 29495625, 2018). "We therefore investigated whether GJA1 expression in primary breast tumor changed with stage and grade at the mRNA level in breast cancer." (PMID 29495625, 2018). "Our results suggest a direct relationship between GJA1 and PR expression in breast cancer samples." (PMID 29495625, 2018). "To evaluate the significance of Cx43 gene expression levels in HER2+ breast cancer, we used the Kaplan-meier plotter database tool (kmplot.com) to assess whether Cx43 (GJA1) gene expression correlates with relapse free survival (RFS) in HER2+ patients." (PMID 29312613, 2017). "Moreover, differential expression of GJA1 has been recently described as a potential positive prognostic marker for a clinically relevant stratification of breast cancer." (PMID 26735887, 2016). "Furthermore, we demonstrate that Runx1 is able to actively promote oncogene Rspo3 and prevent GJA1 gene expression in mammary tumor cell lines." (PMID 26735887, 2016). "Regardless of the precise nature of the link between GJA1 and hormone receptors, our results suggest that GJA1 level is dependent on the overall molecular context provided by each breast cancer subtype and that this might relate to PGR level, at least in some subtypes." (PMID 29495625, 2018). "The worse prognosis associated with GJA1 in Her2e tumors suggests that GJA1 function in breast cancer might not just be tissue- and stage-dependent, as suggested by others, but might also be subtype-dependent." (PMID 29495625, 2018). "Despite this discrepancy, SEH1L, similar to ZYX, GJA1, and TUBA4A, was upregulated in DOX-resistant breast cancer cells in the independent transcriptomic dataset GSE76540." (PMID 41153808, 2025). "YTHDF3 is another organ-specific metastasis driver that regulates the translation of key metastasis genes such as T6GALNAC5, GJA1, EGFR, and VEGFA to promote breast cancer brain metastasis." (PMID 38102722, 2023). "On the other hand, GJA1 expression was higher in tumors than in adjacent normal tissues; and a positive ER status when compared to JGA1 gene expression in breast cancer patients from the cohort." (PMID 36293530, 2022). "Effect of GJA1 on proliferation and EMT ability was also confirmed in breast cancer, lung cancer, and bladder cancer." (PMID 35371339, 2022).